NET1 (neuroepithelial cell transforming 1)
Diseases named in the same sentence as NET1 in open-access papers (continued):
Sharing a sentence is not in itself a finding about the gene and the disease.
cancer (continued). "Examination of in vivo tumors reveals a similar localization of the RAB13 and NET1 RNAs at potential invasive sites, suggesting that this mechanism could provide a targeting opportunity for interfering with collective cancer cell invasion." (PMID 33060293, 2020). "Thus, we concluded that NET1 was significantly higher in hepatic tumors and cancer cell lines, implying its potential role in hepatic tumor growth." (PMID 32641699, 2020). "NET1 functions as a novel regulator of mitosis and occurs in human cancers." (PMID 32420320, 2020). "The Net1 mouse model we used is a whole-body deletion of the Net1 gene, so some of the phenotypes we observed may be due to cancer cell extrinsic as well as intrinsic effects." (PMID 29769144, 2018). "Though Co-expression of Ki67 with NET-1 in tumors was performed to evaluate cancer cell proliferation, the results showed that NET-1 might function with Ki67 to increase tumor cell proliferation." (PMID 24196235, 2014). "Similarly, several reports have correlated the invasive and metastatic potential of cancers with activity and expression of NET-1 in different cancers." (PMID 24196235, 2014). "There was a correlation in NET-1 expression between Ki67 expression (χ2 = 15.2906, r = 0.3430, every P < 0.05), tumor thickness (χ2 = 12.8197, r = 0.3220, every P < 0.05), or cancer differentiation (χ2 = 14.3131, r = 0.0.3542, every P < 0.05)." (PMID 24196235, 2014). "NET1 is involved in cytoskeletal organisation and cancer cell invasion." (PMID 23945136, 2013). "In patients with gastric and OGJ type III tumours, NET1 positive patients were more likely have advanced stage cancer (p = 0.03), had a higher number of transmural cancers (p = 0.006) and had a significantly higher median number of positive lymph nodes (p = 0.03)." (PMID 23945136, 2013). "NET1 knockdown significantly reduced OE33 cancer cell proliferation, migration and invasion." (PMID 23945136, 2013). "It would therefore be of interest to determine if the mislocalization of Ect2 and/or Net1 to the cytoplasm could be a potential resistance factor in human cancers to IR or other DNA damaging agents." (PMID 21373644, 2011). "Net-1 therefore induces metastasis of several types of cancer cells." (PMID 21672235, 2011). "Furthermore, examination of in vivo tumors reveals a similar accumulation of RAB13 and NET1 RNAs at potential invasive sites, suggesting that this mechanism could provide a targeting opportunity for interfering with collective cancer cell invasion." (PMID 33060293, 2020). "The higher expression of NET1 in OE33 OAC cells compared with the other two OAC cell lines may be a reflection of the poor level of differentiation these cells represent, and it has been shown elsewhere that NET1 is seen at high levels in the later metastatic stages of other cancers." (PMID 23945136, 2013). "Previous studies have highlighted the involvement of Rho-A, Net-1, and p38-MAPK in cancer proliferation, invasion, and cell death −." (PMID 39719558, 2024). "The expression of CDK6 can be downregulated as a result of NET-1 protein depression, which provides a therapeutic potential for targeting CDK6 in the treatment of cancer." (PMID 34041269, 2021). "The Cancer Genome Atlas (TCGA) data analysis indicated that the gene expression of TRIO, NET1, ECT2, TIAM2, FARP1, ARHGEF12 and BCR in primary cancer was significantly higher than those in normal tissues." (PMID 32029704, 2020). "Several investigators have previously reported the relevance of TRIO, NET1, ECT2 and TIAM2 in cancer metastasis and clinical prognosis." (PMID 32029704, 2020). "Previous studies have shown that NET-1 expression was related closely to HCC proliferation, with significant upregulation during formation of cancers." (PMID 24885292, 2014). "NET1 is upregulated by Lysophosphatidic Acid (LPA), a known activator of RhoA, and NET1 drives cancer cell migration, invasion and cytoskeletal actin organisation." (PMID 21284875, 2011).
cancer (continued). "In addition, NET-1 expression was obviously correlated with tumor infiltrating; it suggests the accumulation of NET-1in cancer cells closely related to the malignant progress of SSCC." (PMID 24196235, 2014). "In prior study from this laboratory, NET-1, as a new member of TM4SF plays an important role in cell signal transduction, and is closely correlated with proliferation, invasion and poor prognosis of cancers." (PMID 24196235, 2014). "Moreover, the reduced distant metastasis-free survival in patients with a high Net1 gene expression signature was observed in a cohort of patients that was not subdivided according to cancer subtype." (PMID 29769144, 2018).
tumor (27 papers, 2006 to 2025). "Conversely, the radiotracer signal in the Kelly tumour sections was low confirming the association between tumour 18F-mFBG uptake and NET-1 protein expression." (PMID 33262374, 2020). "Loss of E-Cadherin is associated with EMT and tumour invasion and has been linked functionally to NET1 and TGFβ." (PMID 23945136, 2013). "NET1 is significantly up-regulated in gastric and breast cancers, which suggests that bupivacaine is involved in tumor migration via this pathway to inhibit tumor migration." (PMID 34950031, 2021). "Immunohistochemistry analysis revealed that the H-score of NET1 staining in tumor tissue was remarkably higher that of the adjacent normal tissue (P < 0.001)." (PMID 33839702, 2021). "Cox multivariate analysis revealed several risk factors for OS as follows: multiple tumors (P < 0.001), AFP ≥400 ng/ml (P = 0.001), tumor diameter ≥5 cm (P = 0.022), microvascular invasion (P = 0.003) and high NET1 expression (P = 0.007)." (PMID 33839702, 2021). "Therapies that target NET-1 and increase 131I-mIBG uptake into the tumour cells are under investigation." (PMID 33262374, 2020). "The results showed that NET1 was overexpressed in tumor tissues compared with normal tissues derived from Hou Lung." (PMID 32420320, 2020). "We investigated the distribution of the RAB13 and NET1 RNAs in these invasive tumor masses by performing in situ hybridization of tumor tissue sections." (PMID 33060293, 2020). "Among these, one eRNA located ~ 90 kb downstream of the oncogene NET139, which we referred to as NET1-associated eRNA (NET1e, ENSR00000023843), showed the largest expression alteration between tumor and normal samples (fold change = 5.8, FDR = 3.7 × 10–13)." (PMID 31594934, 2019). "It has been shown that the New EST tetraspanin-1, also called as NET-1 (C4.8, Tspan-1, P503S), overexpressed in various human tumor tissues." (PMID 31544556, 2019). "NET-1 gene (treatment group) significantly delayed the growth of tumor size compared to other two groups (p < .0001), showing a significantly increased Emax (p < .05)." (PMID 31544556, 2019). "In conclusion, TNBS conjugated with NET-1 siRNA inhibited tumor growth and prolonged the life of experimental animals." (PMID 31544556, 2019). "Primary tumor cells from wild-type and Net1 KO mice were transplanted into the mammary glands of wild-type, nontumor-bearing mice, and tumor growth and metastasis were assessed." (PMID 29769144, 2018). "Taken together these data indicate that Net1 deletion inhibits tumor angiogenesis and lung metastasis in a tumor cell autonomous nature." (PMID 29769144, 2018). "Net1 knockout tumor cells tended to express slightly more PyMT than wild-type cells, so reduced recruitment cannot be due to effects on PyMT expression." (PMID 29769144, 2018). "Primary tumor cell transplantation indicates that the reduction in tumor angiogenesis and lung metastasis observed upon Net1 deletion are tumor cell autonomous effects." (PMID 29769144, 2018). "Future work will be directed at understanding the mechanism by which Net1 controls tumor angiogenesis." (PMID 29769144, 2018). "On the other hand, the repressed genes corresponded to cell cycle and mitotic regulators, reflecting the reduced proliferation of Net1−/− tumor cells." (PMID 29769144, 2018). "Presumably, Net1 deletion inhibits the secretion of one or more angiogenic factors by the tumor cells." (PMID 29769144, 2018). "As tumor associated factors, the expressions of PCNA and NET-1 are closely related to cell proliferation." (PMID 24885292, 2014). "We have recently shown that Net1 interacts with several members of the Dlg family of tumor suppressors via its PDZ-binding domain." (PMID 21390328, 2011). "These traits are essential for tumor metastasis, thereby supporting a role for NET1 in the disease setting." (PMID 21284875, 2011).
tumor (continued). "Further to our data demonstrating that LPA drives tumour cell invasion through both NET1 and RhoA, we next investigated the role of the cytoskeleton in these processes." (PMID 18827818, 2008). "We have recently identified enhanced NET1 expression in GA in comparison with adjacent normal tissue and we have furthermore shown NET1 to play a role in tumour cell invasion." (PMID 18827818, 2008). "Knockdown of NET1 inhibited tumor growth in mice within 5 weeks of monitoring period." (PMID 33839702, 2021). "Recent studies showed that NET1 play key roles in tumor development." (PMID 33955315, 2021). "In conclusion, the present study demonstrated that the lack of miR-22 is a common event in patients with NSCLC and may serve as a tumor suppressor by endogenously and negatively regulating NET1." (PMID 32420320, 2020). "We further detected the human RAB13 or NET1 RNAs within the tumor mass." (PMID 33060293, 2020). "Image analysis of 18F-mFBG PET data showed correlation to tumour NET-1 protein expression, while further studies are needed to elucidate whether NET-1 upregulation induced by blocking mTOR might be a useful adjunct to 131I-mIBG therapy." (PMID 33262374, 2020). "In light of the effects of AZD2014 treatment on NET-1 expression observed in vitro, we investigated whether 18F-mFBG could capture changes in tumour NET-1 expression following AZD2014 (25 mg/kg/day) treatment in Kelly xenografts (low NET-1)." (PMID 33262374, 2020). "Interestingly, a clear relationship between 18F-mFBG uptake and NET-1 expression was observed in the vehicle treated tumours." (PMID 33262374, 2020). "Although the AZD2014 exhibited suboptimal activity in vivo and more studies are required to validate a more effective primary therapeutic strategy to inhibit tumour progression whilst sensitising cells to 131I-mIBG therapy, the ability of 18F-mFBG to quantify the NET-1 expression was highlighted." (PMID 33262374, 2020). "To assess the contribution of Net1 to tumorigenesis and metastasis, we bred cohorts of mice lacking one or both Net1 alleles, and compared the rate of tumor appearance to that of wild-type MMTV-PyMT mice." (PMID 29769144, 2018). "Net1 is required for maximal RhoA activation within tumors and for primary tumor cell motility." (PMID 29769144, 2018). "Hence, the inhibitory effect of the combination of DAC and net1‐mAb on tumor growth is likely related to their pro‐apoptotic effects, rather than to a change in proliferation or in angiogenesis." (PMID 27378792, 2016). "The overexpression of NET-1 in tumor cells may be closely related to the malignant phenotype of SSCC." (PMID 24196235, 2014). "we have analysed the levels of NET1 mRNA in OAC tumor tissue." (PMID 23945136, 2013). "This attractive characteristic of tumor-specific expression could made NET-1 as potential therapeutic target for HCC." (PMID 24307893, 2013). "So our findings implied that NET-1 may promote tumor proliferation and growth through activating Ras signal transduction pathway, which mediates tumor cell proliferation, differentiation, and survival." (PMID 24307893, 2013). "The effects of altered NET1 and RhoA levels on tumour cell chemotaxis were examined in vitro." (PMID 18827818, 2008). "Besides, LIFU-combined NET-1 siRNA conjugated nanobubble system could effectively inhibit tumor growth and prolong the life of experimental animals." (PMID 34041269, 2021). "High NET1 expression was found to be associated with large tumor size (P = 0.011), high alpha-fetoprotein (AFP) level (P = 0.015), micro metastasis (P = 0.004), portal vein tumor thrombus (PVTT, P = 0.025) and histologic evidence of microvascular invasion (P = 0.025)." (PMID 33839702, 2021). "Therefore, we assessed whether PET imaging could be used to monitor AZD2014-induced alterations in 18F-mFBG tumour uptake by upregulating NB NET-1 expression levels in vivo." (PMID 33262374, 2020).
tumor (continued). "However, the changes of Emax in Cohort A was significant than other groups, suggesting that the NET-1 TNBS could change the structure inside the tumor, and could be detected by SWE." (PMID 31544556, 2019). "However, it is less clear how Net1 influences tumor angiogenesis." (PMID 29769144, 2018). "This apparent contradiction most likely reflects the short delay in tumorigenesis (only 20 days), and the fact that Net1-deleted tumors tended to be fluid filled and less firm, which may have increased their apparent volume when measuring tumor size with calipers." (PMID 29769144, 2018). "Furthermore, the results in vivo suggested that shRNA NET-1 could significantly downregulate the expression of NET-1 in nude mice xenografts models, leading to stunt the tumor growth and downregulate malignant phenotype of tumor." (PMID 24196235, 2014). "In conclusion, this study demonstrates the relationship between NET1 and HCC progression, particularly tumor growth, invasion and metastasis, through the activation of Akt1 signaling pathway." (PMID 33839702, 2021). "We further demonstrated that NET1 promoted the proliferation and metastasis of HCC tumor in vitro and in vivo." (PMID 33839702, 2021). "KALRN, MCF2/Dbl, NGEF/EPHEXIN, ARHGEF7/βPix/COOL-1, CDC42EP2, DOCK9, NET1, TIAM2, ABR, PLEKHG5, RhoBTB2 and PREX1 were identified as being increased at the tumour rim." (PMID 33256106, 2020). "Their role is underscored by the accumulation of mutations in additional regulators of their activation during the course of this tumor's treatment: MAPK (SPRY3), PI3K (DEPDC5), and WNT (KREMEN2, NET1, GPR124)." (PMID 29440180, 2018). "NET-1 RNAi used in this study can specifically and effectively downregulate NET-1 gene expression; thus SSCC proliferation, invasion and tumor growth were attenuated." (PMID 24196235, 2014). "The importance of NET1 in tumour cell chemotaxis was further demonstrated using the trans-well system, whereby AGS cells, in which NET1 knockdown has been achieved, were shown to be less migratory and invasive in vitro." (PMID 18827818, 2008). "Furthermore, NET1 expression was closely related to some clinical features of HCC cases, including AFP, tumor size, micro metastasis, microvascular invasion and PVTT, which are the most important clinical markers in the progression of HCC." (PMID 33839702, 2021). "In conclusion, we found that the TNBS conjugated with NET-1 siRNA could affect the growth of the tumor, and SWE provided a noninvasive and real-time imaging method to detect the potential changes in the tumor development." (PMID 31544556, 2019). "This analysis indicated that tumors with Net1 deletion exhibited an increased necrotic area regardless of tumor size." (PMID 29769144, 2018). "It is unclear why there was not a significant increase in the survival of mice with Net1 deletion, given the observed delay in tumor initiation." (PMID 29769144, 2018). "In aggregate our data provides strong evidence that NET1 is biologically active in OAC and may be an important factor in promoting an aggressive tumour cell phenotype." (PMID 23945136, 2013). "They further characterized one of these 3′ UTR shortening genes, NET1, and found that the NET1 isoform with a short 3’UTR had stronger in vitro cell migration and invasion capabilities than that with a long 3’UTR, suggesting that APA plays a role in tumor metastasis." (PMID 33526057, 2021). "Also, less tumor foci was detected in the infused/non-infused lobes of NET1 silencing mice compared to normal mice." (PMID 33839702, 2021).
adenocarcinoma (3 papers, 2013 to 2022). A common cancer characterized by the presence of malignant glandular cells. "The Neuroepithelial Cell Transforming Gene 1 (NET1) gene is associated with promoting migration in adenocarcinoma in vitro." (PMID 36612205, 2022). "We showed that type I (Siewert classification) oesophago-gastric junction (OGJ) adenocarcinomas expressed significantly higher levels of NET1, with lowest expression in type III and intermediate levels in type II (p = 0.01)." (PMID 23945136, 2013). "Looking at other in vitro GI cancer models, the OE33 cell line had greater NET1 mRNA expression compared to gastric (AGS) and colorectal (SW480) adenocarcinoma models." (PMID 23945136, 2013).
NET1 also shares sentences with these, for which no sentence is quoted: non-small cell lung carcinoma (2 papers); alcohol dependence (1); cardiac sarcomas (1); cervical squamous cell carcinoma (1); Cirrhosis (1); coronary artery disease (1); diabetic kidney disease (1); dilated cardiomyopathy (1); endothelial dysfunction (1); gastrointestinal stromal tumor (1); head and neck squamous cell carcinoma (1); heart failure (1); hemorrhage (1); Hypertension (1); intestinal tumor (1); ischemic cardiomyopathy (1); sarcoma (1); skin squamous cell carcinoma (1); spindle-cell carcinoma (1); uremia (1).